AHR (aryl hydrocarbon receptor)
Diseases named in the same sentence as AHR in open-access papers (continued):
Sharing a sentence is not in itself a finding about the gene and the disease.
gastric cancer (continued). "An immunohistochemical study reported gradually increasing levels of AhR expression, with the lowest levels in superficial gastritis, followed by chronic atrophic gastritis, intestinal metaplasia, atypical hyperplasia, and gastric cancer." (PMID 31226941, 2019). "The overexpression of aryl hydrocarbon is evident during gastric carcinogenesis; thus, modulation of the AhR may contribute to restraining gastric cancer growth." (PMID 27447608, 2016). "Herein, we hypothesize that Biseugenol inhibits the EMT progression of gastric cancer cells through a Calpain-10- interaction with AhR and regulated Snail pathway." (PMID 25226618, 2014). "Both Tunicamycin (3-5 μg/ml) and Eug (40 μM) could also enhance the expressions of Grp78, p-elf2α, and DR5 and reduce the expression of AhR in gastric cancer cells." (PMID 25226618, 2014). "Our previous work found that the expression of AhR was significantly up-regulated in gastric cancer, and may be involved in the early stage of gastric carcinogenesis, regulation of the AhR pathway may have a potential role in the treatment of gastric cancer." (PMID 22592002, 2012). "Taken together, these results suggest that DIM could activate the AhR signal pathway in gastric cancer cells." (PMID 22592002, 2012). "Then our futher studies showed that TCDD, a potent AhR agonist, could supresse the growth of gastric cancer cell AGS in a dose- and time-depengent manner via induction of growth arrest at the G1-S phase." (PMID 22592002, 2012). "AhR expression is upregulated in lung, mammary gland, pancreatic and gastric cancers." (PMID 22592002, 2012). "However, the relationship between AhR pathway activation and gastric cancer progression is still unclear." (PMID 19371443, 2009). "In present study, we used 2,3,7,8-tetrachlorodibenzo-para-dioxin (TCDD), a classic and most potent ligand of AhR, to activate AhR pathway and investigated the effect of AhR pathway activation on human gastric cancer AGS cell invasion and explored the corresponding mechanism." (PMID 19371443, 2009). "To determine if AHR suppresses NF-κB activation in gastric cancer (GC) cells, we performed Co-IP assays in HGC27 cells." (PMID 41208900, 2025). "Our findings suggested that AhR might be a promising target for gastric cancer treatment." (PMID 22592002, 2012). "AhR may be a potential therapeutic target for gastric cancer treatment." (PMID 22592002, 2012). "Therefore, we investigated the effect of AhR pathway activation on human gastric cancer cells." (PMID 19371443, 2009). "Thus, the NLRP3 inflammasome promotes gastric cancer and its downregulation by the activity of the aryl hydrocarbon receptor (AhR), dopamine receptor D1 (DRD1) and G protein-coupled bile acid receptor 1, (GPBAR1) may limit the occurrence of pyroptosis, thereby affecting cancer progression." (PMID 37081882, 2023). "The activation of AHR and CYP1A1 and CYP1B1 related pathways promotes the proliferation and migration of gastric cancer cells." (PMID 34784845, 2021). "AHR activation with TCDD induces MMP-9 expression and gastric cancer cell invasiveness, an effect likely mediated through a c-Jun-dependent pathway." (PMID 33396563, 2020). "Our previous work found that an AhR agonist, 2,3,7,8 –tetrachlorodibenzo -para-dioxin (TCDD), inhibited gastric cancer cell growth." (PMID 22592002, 2012). "AHR activation inhibits MTDH phosphorylation at Ser298, which in turn suppresses nuclear factor kappa B (NF-κB) signaling pathway activity, ultimately attenuating gastric cancer progression." (PMID 41208900, 2025). "Metabolites, such as L-kynurenine, might enhance ferroptosis in NK cells through aryl hydrocarbon receptor and mediate immunosuppressive TME in gastric cancer." (PMID 40464376, 2025). "This ECM-related mechanism, if it takes place in vivo, may explain the resistance of gastric cancer to CAR-T cell therapy and implies a possibility to improve the therapeutic effect by neutralizing KynA or by inhibiting the AHR pathway." (PMID 39996879, 2025).
gastric cancer (continued). "However, the role of AhR on EMT and cellular and molecular mechanisms of the development, progression, and peritoneal dissemination in gastric cancer still remain to be clarified." (PMID 25226618, 2014). "We also assessed transfected Calpain-10 siRNA knocks down the co-localization of endogenous Calpain-10/AhR in Biseugenol-treated gastric cancer cells (data not shown)." (PMID 25226618, 2014). "To test wether the AhR signal pathway could be activited by DIM in gastric cancer cells, we treated gastric cancer cell line SGC7901 with DIM." (PMID 22592002, 2012). "To test whether the AhR signal pathway could be activated by DIM, we treated the gastric cancer cell line SGC7901 with DIM." (PMID 22592002, 2012). "In surmary, this report showed that non-toxic selective AhR modulator DIM inhibited the proliferation of human gastric cancer cell line SGC7901 in vitro by inducing cell apoptosis and arresting cell cycle at G1 phase." (PMID 22592002, 2012). "Therefore, since we observed a higher expression of IDO1 and TDO2 in gastric cancers as compared to non-tumoral tissue, we further analyzed AhR expression and protein localization in gastric tumors." (PMID 35203450, 2022). "But TCDD itself is carcinogenic, So to find non-toxic or low-toxic AhR modulators may be a new direction for molecular-targeted therapy in gastric cancer." (PMID 22592002, 2012). "However, the relationship between AhR pathway activation and gastric cancer invasion and metastasis is still not clear." (PMID 19371443, 2009). "Additionally, AhR may be a useful prognostic marker for gastric cancer and novel therapeutic targets for gastric cancer invasion intervention." (PMID 25226618, 2014). "This is in contrast to a previously published model of constitutive AHR activation in which a construct lacking the PAS-B domain was expressed as a transgene under a heterologous promoter, resulting in the development stomach cancer." (PMID 40502009, 2025). "Gastric cancer cell SGC7901 was treated with DIM at different concentrations (0,10,20,30,40,50 μmol/L) with or without an AhR antagonist, resveratrol." (PMID 22592002, 2012).
pancreatic cancer (36 papers, 2013 to 2025). "AhR expression is markedly elevated in patients with pancreatic cancer compared with healthy controls, and high AhR expression is associated with accelerated disease progression and enhanced immunosuppression." (PMID 41332472, 2025). "Studies in pancreatic cancer suggest that tryptophan-derived metabolites can activate the aryl hydrocarbon receptor (AHR) in tumor-associated macrophages, leading to reduced anti-tumor immunity." (PMID 40624207, 2025). "In a pancreatic cancer mouse model, TAMs demonstrated high AhR activity, and a reduction in AhR deficiency activity in TAMs led to a more inflammatory phenotype associated with control of tumor growth." (PMID 38339226, 2024). "Interestingly, specific intratumoral microbes promote AhR expression in pancreatic cancer, whereas AhR deficiency increases MHC-II, CD40, and PD-L1 expression in the TME." (PMID 41326352, 2025). "Furthermore, AhR is expressed by tumor-associated macrophages where its activation by Lactobacillus-metabolized tryptophan metabolites drives immunosuppression and pancreatic tumor growth." (PMID 38807762, 2024). "In pancreatic cancer cells, the activation of AhR/EZH2 signaling axis causes epigenetic alteration." (PMID 36635272, 2023). "TCDD exposure resulted in a significant increase in MALAT1, EZH2, and H3K27me3 levels but exposure to AhR antagonists exhibited the reversed functions of MALAT1, EZH2, and H3K27me3 in AhR-overexpressing pancreatic cancer cells." (PMID 40765830, 2025). "In particular, it has been reported that ELAVL1 interacts with AHR mRNA to increase gemcitabine sensitivity in pancreatic cancer cells." (PMID 39588852, 2025). "Carbidopa, an FDA-approved drug for Parkinson’s disease, acts as an AHR agonist, impeding the growth of pancreatic cancer cells by inhibiting IDO1 (indoleamine 2,3-dioxygenase-1)." (PMID 38612627, 2024). "In pancreatic cancer, macrophage-specific deletion of AhR or AhR inhibition impaired tumor growth, improved the efficiency of checkpoint blockade therapy, and increased infiltration of CD8+ T cells." (PMID 38339226, 2024). "High levels of IDO, TPH1, HTR2B, AhR, and Kyn predict a poor prognosis in pancreatic cancer, whereas MAOA expression is negatively correlated with TNM stage and tumor size in pancreatic cancer, predicting a favorable prognosis." (PMID 38462620, 2024). "Depletion of AHR using small interfering RNAs targeting AHR in pancreatic cancer cells heightens sensitivity to gemcitabine, a chemotherapeutic agent, and diminishes cells’ invasive and migratory potential." (PMID 38612627, 2024). "Nitric oxide activates the IDO1/ kynuridine /AhR signaling axis, promoting pancreatic cancer progression." (PMID 38462620, 2024). "We observed the presence of the AhR-Nrf2 axis in pancreatic cancer 2545 cells and that Jdp2 plays a crucial role in pancreatic cancer progression." (PMID 37596694, 2023). "In conclusion, our study was the first to reveal the induction of the AHR signaling pathway by IPA in an ex vivo tissue explant model of human pancreatic cancer." (PMID 36671030, 2023). "Carbidopa, another antiparkinsonian medication, has also been shown to be effective against pancreatic cancer by the inhibition of indoleamine-2,3-dioxygenase-1 and the potentiation of aryl hydrocarbon receptor signaling." (PMID 37847564, 2023). "Future research should address these limitations to provide a more comprehensive understanding of the relationship between AHR expression, immune dysregulation, and pancreatic cancer." (PMID 37760608, 2023). "IDO1/TDO dual inhibitor RY103 targeted the Kyn-AhR pathway in mice xenografted with pancreatic cancer cells." (PMID 37830596, 2023).
pancreatic cancer (continued). "The effects of DRE-mediated transactivation of Jdp2 on the AhR promoter were investigated in the pancreatic cancer 2545 cell line." (PMID 37596694, 2023). "We have already identified carbidopa, an FDA-approved drug for Parkinson's disease, to have an anticancer effect in pancreatic cancer via its role as an AhR agonist." (PMID 35997090, 2022). "Our published studies have established the anti-cancer efficacy of carbidopa in pancreatic cancer and also have discovered that carbidopa is an agonist for the nuclear receptor AhR." (PMID 35997090, 2022). "We have already shown that carbidopa is an AhR agonist and that it inhibits pancreatic cancer growth." (PMID 35997090, 2022). "In patients with pancreatic cancer, a direct correlation between the plasma level of AhR with age and BMI was observed, specifically in pancreatic cancer patients > 65 years old and BMI < 25 kg/m2." (PMID 36418969, 2022). "A high level of AhR protein has also been reported in pancreatic cancer, endometrial cancer, and meningioma." (PMID 33451095, 2021). "Carbidopa activates AHR by serving as its agonist ligand, thereby promoting its downstream target gene activation and inhibiting pancreatic cancer growth." (PMID 32404918, 2020). "Studies in this laboratory have previously reported that omeprazole inhibits invasion of breast and pancreatic cancer cells and these responses were AhR-dependent." (PMID 32731514, 2020). "Results of other studies in breast and pancreatic cancers cells further demonstrate that the AhR activities of pharmaceuticals are highly selective." (PMID 32932962, 2020). "Higher AhR expression has been observed in stomach, thyroid, colon and pancreatic tumors whereas in breast, lung, prostate and cervical cancer AhR mRNA level was similar to non-tumor tissue." (PMID 32899152, 2020). "The activation of AhR can lead to cell cycle arrest and growth inhibition of pancreatic cancer cell lines through induction of the cyclin-dependent kinase inhibitor p21." (PMID 29734388, 2018). "Similarly, omeprazole, functioning as an AHR agonist, hampers the migration and invasion of pancreatic cancer cells." (PMID 38612627, 2024). "Human pancreatic cancers highly express IDO1 and TDO, which correlate with poor patient prognosis, and causes increased migration and invasion of cells and spheroids via kynurenine-mediated AhR activation." (PMID 38807762, 2024). "AhR has also been found to modulate pancreatic cancer progression." (PMID 38807762, 2024). "Ultimately, this study may contribute to the development of effective treatments for pancreatic cancer by targeting AHR signalling pathways to modulate immune responses and improve patient outcomes." (PMID 37760608, 2023). "Increased AHR expression can be seen in many different malignancies, for example, lymphoma and leukaemia, as well as breast, kidney, gastrointestinal, and pancreatic cancers." (PMID 37685961, 2023). "Therefore, we investigated the possible link between the expression of PD1/PDL1 and AHR genes in PBMCs of pancreatic cancer patients." (PMID 37760608, 2023). "Moreover, plasma AhR levels are higher in the male patients with pancreatic cancer than in the female patients with pancreatic cancer." (PMID 37749614, 2023). "Studies in this laboratory have also focused on repositioning AhR pharmaceuticals for chemotherapeutic applications in both breast and pancreatic cancer and have demonstrated that inhibition of tumor invasion and metastasis by OME and tranilast was AhR-dependent by tumor-specific mechanisms." (PMID 32731514, 2020).
pancreatic cancer (continued). "Some AHR agonists inhibit the growth of pancreatic cancer cells expressing AHR at high levels." (PMID 26392334, 2015). "Thus, while exogenous AhR activation appears to have a tumor suppressive effect, emerging evidence suggests that endogenous ligands may promote pancreatic cancer progression." (PMID 38807762, 2024). "However, more recent studies have suggested a tumor promoting role for AhR in pancreatic tumors." (PMID 38807762, 2024). "Meanwhile, AhR activation could enhance the EZH2 activity and increase its epigenetic silencing activity, which is a risk factor for environmental toxicant-associated pancreatitis and pancreatic cancer." (PMID 36635272, 2023). "For example, carbidopa, an AhR agonist, suppresses IDO1 expression in pancreatic cancer cells, attenuating tumor growth." (PMID 41332472, 2025). "This work has shown that AhR activation by agonists – including TCDD, MCDF, and DIM – suppresses the growth of pancreatic cancer cells." (PMID 38807762, 2024). "Carbidopa, an AhR agonist, inhibits IDO1 expression in PDAC cells, regulating the JAK/STAT pathway to impede pancreatic cancer progression." (PMID 38462620, 2024). "The top pathways suggested tRNA splicing, vitamin C transport, apelin liver signaling, metabolism of aryl hydrocarbon receptor (AHR) signaling, glycoprotein VI platelet (GP6) signaling, and SPINK1 pancreatic cancer pathway." (PMID 34685781, 2021). "AHR displays heightened expression in the cytoplasm of pancreatic cancer tissues, and its activation by AHR agonists such as DIM (diindolymethane) inhibits the growth of pancreatic cancer cells." (PMID 38612627, 2024). "Previous studies have not yet explored the changes in anticancer immunity and AHR expression, specifically in the blood of pancreatic cancer patients." (PMID 37760608, 2023). "Additionally, role of AhR and MALAT1 can be studied in pancreatic cancer model by inoculation of AhR-overexpressing pancreatic cancer cells." (PMID 37830596, 2023). "The top five pathways according to p value were SPINK1 Pancreatic Cancer Pathway, EIF2 Signaling (p = 1.05E−7), Aryl Hydrocarbon Receptor Signaling (p = 1.05E−7), Clathrin-mediated Endocytosis Signaling (p = 2.3E−7), and Actin Cytoskeleton Signaling (p = 2.44E−7)." (PMID 35780404, 2022). "The top five pathways according to p value were SPINK1 Pancreatic Cancer Pathway, BAG2 Signaling Pathway (p = 9.20E−8), Aryl Hydrocarbon Receptor Signaling (p = 4.22E−7), Clathrin-mediated Endocytosis Signaling (p = 7.81E−7), and Protein Ubiquitination Pathway (p = 8.22E−7)." (PMID 35780404, 2022). "For example, in pancreatic cancer cells the AhR-active pharmaceuticals omeprazole and tranilast but not TCDD inhibited invasion of Panc1 pancreatic cancer cells, and this response was AhR-dependent." (PMID 32932962, 2020). "However, the effects of ligand-dependent AHR activation or inhibition on pancreatic cancer cell proliferation, invasion, and migration have not been investigated." (PMID 38612627, 2024). "In pancreatic cancer, the AhR ligand kynurenine increased expression of multiple anti-apoptotic proteins, including XIAP and B-cell lymphoma 2 (Bcl-2), while decreasing the pro-apoptotic protein bax, which was abrogated with the addition of the AhR inhibitor CH-223191." (PMID 38339226, 2024). "We next investigated the effects of several AhR-active pharmaceuticals including leflunomide, mexiletine, tranilast, β-naphthoflavone, the AhR active microbial metabolite tryptamine, and OME, a pharmaceutical that inhibits invasion of breast and pancreatic cancer cells." (PMID 32731514, 2020). "Interestingly, pancreatic cancer patients were statistically significantly younger in the Low AHR group, although the gender proportion remained similar regardless of the AHR level." (PMID 37760608, 2023).